HIF1A (hypoxia inducible factor 1 subunit alpha)
Diseases named in the same sentence as HIF1A in open-access papers (continued):
Sharing a sentence is not in itself a finding about the gene and the disease.
tumor (continued). "HIF1α is often overexpressed in HCC, promoting tumor growth, metastasis, and drug resistance, with increased expression associated with poor patient outcomes." (PMID 38666828, 2024). "Meanwhile, up-regulated HIF-1α bound to the promoter of HPRT1 and transcriptionally activates HPRT1 expression, enhancing purine metabolism to maintain rapid tumor cell proliferation in EGFR-mutant LUAD." (PMID 39343971, 2024). "Three HIF-α proteins (HIF-1α, HIF-2α, and HIF-3α) mediate the adaptive transcriptional response to hypoxia in both normal and tumor cells." (PMID 38544822, 2024). "In gliomas, bladder cancer, and various other tumors, the expression levels of HIF1α, GLUT1, and GLUT3 are elevated, and these levels are correlated with tumor prognosis." (PMID 39769177, 2024). "This polysaccharide inhibits VEGF and HIF-1α expression by targeting the PI3K/AKT/mTOR pathway, suggesting a novel strategy for tumour growth suppression." (PMID 39683144, 2024). "As JHU083 is known to affect c-MYC and HIF-1α signaling, we investigated c-MYC and HIF-1α expression levels in MB49 tumor/stromal cells." (PMID 38701369, 2024). "HIF1α stimulated Glu uptake, glycolysis, and lactate production by upregulating GLUT1, HXI, and LDH, promoting cell proliferation and tumor growth." (PMID 38786726, 2024). "Previous studies have demonstrated that HIF1α stabilization was adequate to induce an iCAF phenotype and enhance PDAC tumor growth, offering a theoretical foundation for the potential differentiation of iCAFs within our comPDAC-FPCL model." (PMID 38612551, 2024). "NRF2 silencing has been shown to decrease HIF-1α levels, suppressing HIF-1α-driven processes such as cell proliferation, angiogenesis, tumor growth, and migration/invasion." (PMID 39796470, 2024). "Armed with HIF‐1α downregulation by Tanespimycin, TISN reversed the immunosuppressive tumor microenvironment and ultimately achieved a superior inhibition in both local and abscopal tumors by this synergistic mitochondria‐targeted PIT strategy." (PMID 39525955, 2024). "miR-17-92 exerts its inhibitory effect on the progression of CRC by reducing tumor angiogenesis which is achieved by targeting several tumor angiogenesis-inducing genes, including TGFBR2, HIF1α, and VEGFA, both in vivo and in vitro." (PMID 38534736, 2024). "Both HIF-1α and VEGF exhibited a remarkably similar distribution with CA-IX in GBM, which is regulated by HIF-1α, similar to VEGF, and correlated with tumor grade." (PMID 39055895, 2024). "This suggests the positive correlation of HIF1α with the CD8+ T cell exhaustion, exerting oncogenic roles and exacerbating tumor metastasis." (PMID 38361941, 2024). "G-Rh2 has been shown to target HIF-1α and downregulate PDK4 expression, thus inhibiting tumor glycolysis." (PMID 38671369, 2024). "While TCM from untreated BC cells induced increased expression of VEGFR2, VEGFA, FGFR1, HIF-1α and PDGFRB, this effect was significantly inhibited by the muscone administration to tumor cells prior to isolation of the 231TCM and 549TCM." (PMID 38898449, 2024). "Hypoxia, a common feature of the tumor microenvironment, profoundly impacts CAR T cell function, emphasizing the need to explore strategies targeting hypoxia-inducible factor-1α (HIF-1α)." (PMID 38425341, 2024). "In terms of the mechanism, we found that miR-21-5p carried by TAM-EVs activated HIF-1α in ECs through VHL and LATS1, forming a YAP1/HIF-1 positive loop, which plays a crucial role in promoting tumor angiogenesis." (PMID 38602536, 2024). "Quantitative PCR analysis of tumor tissues demonstrated that rAd.DCN + NK combination treatment significantly upregulated perforin and IFN-γ expression and downregulated HIF-1α expression compared to rAd.DCN or NK monotherapy groups." (PMID 39482550, 2024). "Tumor-infiltrating EPCs contributes to resistance against anti-VEGF therapy by indirectly secreting TGF-β, HIF-1α, and VEGF as angiogenesis-promoting growth factors." (PMID 38611849, 2024).
tumor (continued). "HIF-1α also plays a direct role in upregulating immune checkpoint key players, including CTLA-4, LAG3, TIM3, and PD-L1 on tumor cells, as well as PD-1 and VISTA on MDSCs." (PMID 38396737, 2024). "HIF-1α RNAi visibly reduced the expression of HIF-1α and VEGF, suppressed tumor angiogenesis, and attenuated metastasis." (PMID 39204162, 2024). "In the context of hypoxia response, UBXD7’s targeting of HIF-1α for degradation via interactions with the p97 complex and CUL2/VHL E3 ubiquitin ligase complexes open new avenues for targeting hypoxic tumours." (PMID 38365777, 2024). "Stable expression of HIF-1α during hypoxia promotes the metabolic shift from OXPHOS to glycolysis in NK cells, overcoming hypoxia-mediated apoptosis and tumor cytotoxicity damage in NK cells maximizing NK cell effector function." (PMID 38433193, 2024). "For example, hypoxia-inducible factor 1-alpha (HIF1-α) and vascular endothelial growth factor (VEGF) were highly expressed in the inner tumor layers, which promoted endothelial cell proliferation and migration, in contrast to the non-hypoxic outer layers." (PMID 39770196, 2024). "Furthermore, mitochondrial dysfunction can affect multiple signaling pathways, such as HIF-1α and NF-κB, as well as the transmission of communication mediators including cytokines, exosomes, and proteins, thereby influencing the interaction between tumor cells and immune cells." (PMID 39130746, 2024). "The same trend was observed for the reduction of lung metastasis and decrease in expression of HIF-1α, MMP-2, and MMP-9 and lactate levels in the tumor tissue." (PMID 39138299, 2024). "It has been demonstratedthat hypoxia-induced dimerization of HIF1-α and HIF1-βwithin nuclei plays a crucial role in tumor metastasis." (PMID 39651070, 2024). "HIF-1α, HIF-2α, and HIF-3α H-expression levels in relation to tumor grade, TNM stage, and tumor size in 150 patients with ccRCC." (PMID 38571885, 2024). "Further spatial transcriptomic (ST) data from six tumor samples indicated a significant spatial co‐expression between IER2 and HIF‐1α." (PMID 39207055, 2024). "Propofol downregulates HIF1α expression in GB and enhances the sensitivity of GB cells to TMZ, reducing tumor growth, macrophage infiltration, and inflammation in TMZ-resistant GBM xenograft tumors." (PMID 38786726, 2024). "These C/Q@ZIF-8-HA nanozymes, while efficiently targeting tumor cells, significantly decrease HIF-1α by reducing intracellular and TME hypoxia, thus enhancing X-ray killing of tumor cells." (PMID 38195456, 2024). "In conclusion, the differential expression of EGLN and HIF1A genes in HNSCC tumors compared to normal tissues influences patients’ overall survival, highlighting their role in tumor development." (PMID 38928200, 2024). "In cancer cells, PKM2 activates the transcription of HIF-1α and its target gene VEGF in the nucleus; this stimulates the secretion of VEGF to promote angiogenesis and enhance tumor growth." (PMID 39411137, 2024). "Through HIF‐1α/RhoA/ROCK1 signaling, DDR1 promoted cytoskeleton reorganization to induce tumor metastasis." (PMID 39024501, 2024). "In this regard, when the tumor volume reached about 500 mm3, HMW and LMW CS NPs containing either anti-HIF-1α siRNA2 or scrambled siRNA were injected twice, 24 h and 4 h before culling the mice." (PMID 39458615, 2024). "In pancreatic cancer, hypoxia/HIF1α upregulates lncRNA BX111 to promote the transcription of ZEB1, a key regulator for epithelia–mesenchymal transition (EMT), to facilitate tumor metastasis and progression." (PMID 38485986, 2024). "Inhibiting HIF1α and LGMN enhances CD8+ T cell- anti-tumor immunity, impairs GBM tumor progression, and improves immunotherapy responses (anti-PD1 therapy) in mice." (PMID 38994360, 2024). "HIF-1α upregulates the translocation of GLUT, such as GLUT1 and GLUT3, to the cell membrane, thereby promoting glucose uptake into tumor cells for glycolysis." (PMID 38544822, 2024).
tumor (continued). "The master regulator of this specific step of tumor progression is, indeed, HIF-1, which is constituted of two distinct parts: an oxygen-sensitive HIF-1α subunit and a constitutive HIF-1β subunit." (PMID 39334716, 2024). "Suppression of the HIF-1α gene or inhibition of its transcription can hinder tumor cells from secreting vascular endothelial growth factor (VEGF) and impede tumor neovascularization." (PMID 38799423, 2024). "In summary, the MOF metal framework MIL-101 (Fe) was chemically bonded to the HIF-1α inhibitor ACF and coated with the plasma membrane of tumor cells to synthesize the MOF nanoparticles MIL-101/ACF@CCM." (PMID 38794281, 2024). "We transfected the tumor cells with miR-6883 using lipofectamine RNAiMAX and measured protein levels of CDK4/6 and HIF1α by western blot." (PMID 38344066, 2024). "In the hypoxic tumor microenvironment, HIF-1α upregulates GLUT-1 expression, and the observed positive correlation between HIF-1α and GLUT-1 expression suggests potential crosstalk between these proteins." (PMID 39202223, 2024). "Factors such as HIF-1α and VEGF drive angiogenesis under hypoxic conditions, often contributing to aggressive tumor behavior and poor prognosis." (PMID 39595235, 2024). "When PCa is in a hypoxic tumor microenvironment, both FOXA1 and FOXA2 regulate the hypoxic transcriptional program by binding to HIF1A." (PMID 38605023, 2024). "Our findings indicate that the overall expression of FAK, HIF-1α, Ki67, and CD44 was higher in tumor nests, whereas that of ILK was higher in tumor stroma." (PMID 38727811, 2024). "While HIF-1α expression is typically upregulated, HIF-2α expression is downregulated in tumor tissues." (PMID 39459028, 2024). "In the animal study, the orally administered HIF-1α inhibitor, PX-478, significantly reduces PDLIM2 knockdown-promoted tumor growth." (PMID 38880883, 2024). "Thus, this review elucidates the link between PTEN and angiogenesis through HIF-1-α and highlights that instead of directly targeting tumor angiogenesis, the tumor suppressor, PTEN, could be upregulated using phytochemicals, resulting in the ubiquitylation of HIF-1-α and a reduction in angiogenesis." (PMID 38338464, 2024). "HIF-1α is one of the isoforms of the 92 kDa HIF protein, and plays a part in carcinogenesis and tumor growth by regulating genes involved in angiogenesis, metabolism, and other biological mechanisms." (PMID 39275392, 2024). "Next, we performed IHC to assess the relationship between HIF‐1α and H3K27me3 in NSCLC tumor tissue." (PMID 38072662, 2024). "Hypoxia-inducible factors (HIF), particularly HIF-1α and HIF-2α, are key regulators of cellular oxidation levels and play a pivotal role in tumor responses to hypoxia." (PMID 39061859, 2024). "Increased expression of vascular endothelial growth factor-A (VEGF-A) and hypoxia-inducible factor-1α (HIF-1α), a tissue inhibitor of metalloproteinases-1 (TIMP-1), was observed in tumorous samples compared to adjacent normal tissues." (PMID 39062015, 2024). "This reduction was accompanied by decreased protein levels of HIF-1α, PD-L1, VEGF, and p-STAT3 in the tumor tissues." (PMID 39690423, 2024). "Upon entering the cell nucleus, HIF-1α and HIF-1β combine to form a heterodimer, which binds to hypoxia response elements (HRE, 5′-TACGTGCT-3′) present in multiple genes related to tumor progression." (PMID 38766303, 2024). "Since CXCR4 levels were elevated in tumor and vascular cells of GBM, it was suggested that pseudopalisade cells around hypoxic areas of necrosis overexpress CXCR4 under the control of HIF-1α." (PMID 39055895, 2024). "In cancer cells, activation of IRE1α in combination with HIF1α promotes resistance to hypoxia; it also regulates cellular metabolism by expressing GLUT1 and LDHA, allowing tumor cells to consume glucose and enhance glycolysis." (PMID 39596467, 2024).
tumor (continued). "TH-302 (Evofosfamide) (NCT02076230) targets hypoxic tumor cells and PX-478 (NCT00522652) acts by inhibiting hypoxia-inducible factor-1 alpha (HIF-1α)." (PMID 39239563, 2024). "Meanwhile, hypoxia‐inducible factor‐1 alpha (HIF‐1α) can directly activate PKM2 transcription and indirectly upregulate its expression ALYREF‐dependently to produce tumor‐promoting effects." (PMID 39584783, 2024). "There were also significant differences in the expression of HIF-1α, which was lower in the SCP NPs group and higher in IR-780 groups, indicating that the nanoparticles delivered oxygen to the tumor to relieve hypoxia." (PMID 39104624, 2024). "To investigate potential differences in DNA methylation between tumor and adjacent normal tissues based on TCGA data, we utilized the UALCAN database to visualize promoter DNA methylation status in HIF1A and EGLN1-3 genes among HNSCC patients." (PMID 38928200, 2024). "CCL17 expression in M2 macrophages can activate Wnt/β-catenin signaling and promote EMT of tumor cells, while tumor cells in turn activate TAMs through the TLR4/TRIF/NF-κB signaling pathway and increase IL-1β production mediated by HIF1α to trigger EMT." (PMID 38957393, 2024). "The activation of HIF-1α increases the expression of angiogenic factors and influences ECM degradation and remodeling, releasing growth factors that promote tumor angiogenesis and cell survival." (PMID 39684583, 2024). "The anti-angiogenesis potential of MSC Exos in the context of tumor parenchyma leads to the reduction of VEGF, inhibition of NF-κB, and mTOR/HIF1A/VEGF axis." (PMID 38360641, 2024). "Hypoxia, induced by HIF-1α, triggers PDL-1 (CD274) expression in tumor and immune cells, thus promoting immune suppression in the TIME." (PMID 39119332, 2024). "Therefore, HIF-1α may exert a tumor suppressor function in the context of RCC." (PMID 38928435, 2024). "Subsequently, the ability of ACF release to inhibit tumor cell migration was evaluated through cell immunofluorescence experiments, which revealed that MIL-101/ACF@CCM effectively suppressed HIF-1α expression." (PMID 38794281, 2024). "The HIF-1α inhibitor, IDF-11774, achieved similar results in a nude mouse B16-F10 model, diminishing tumor growth and increasing CD8+ T cell infiltration." (PMID 38426087, 2024). "A liposome composed of the HIF-1α inhibitor vitexin and PS indocyanine green (ICG) showed potent inhibition of the tumor cells and suppression of their migration in a dose-dependent manner." (PMID 39201395, 2024). "For example, HIF-1α enhances the production of matrix metalloproteinases (MMPs) and other enzymes that break down the extracellular matrix (ECM), enabling tumor cells to more efficiently penetrate the surrounding brain tissue." (PMID 39272834, 2024). "Both HIF-1α and TGF-β actively regulate angiogenesis, which is crucial for tumor growth and metastasis." (PMID 38542288, 2024). "The inhibition of hypoxia-induced HIF-1α suppresses the migration, invasion, and EMT of tumor cells." (PMID 38904007, 2024). "Conversely, inhibition of HIF-1α expression levels triggered the down-regulation of YY1, resulting in increased sensitivity of tumor cells to chemotherapeutic agents." (PMID 37588219, 2024). "Remarkably, administration of acriflavine (ACF), a HIF1α inhibitor, to mice bearing A549HOIPOE cells significantly mitigated tumor burden." (PMID 38272870, 2024). "Antisense HIF-1α treatment inhibits HIF-1α expression through antisense gene transfer, resulting in the downregulation of VEGF translation and reduced tumor micro-vessel density." (PMID 39459028, 2024). "In this model, HIF-1α and HIF-2α were chosen based on their importance of how tumor cells can adapt to changes in oxygen gradients and spheroids are able to functionally adapt to those gradients (death and necrosis vs. adaptation and progression)." (PMID 39669700, 2024).
tumor (continued). "HIF-1α, VEGF, and VEGFR expression were identified in both GBM and peritumoral tissue, but HIF-1α and VEGF expression increased in cells within the tumor, whereas VEGFR density was low in both tumoral and peritumoral tissue cells." (PMID 39055895, 2024). "By enhancing MCT-4 expression and the glycolytic rate, lactate promotes M2 polarization by inducing arginase-1 (Arg1), HIF-1α, IL-6, and transcriptional repressors such as ICER, which negatively influence anti-tumor responses." (PMID 38891772, 2024). "In neutrophil‐1, overexpression of HIF1A enhanced VEGF expression in response to hypoxia, and the activation of CSF3R‐NAMPT‐STAT3 signalling augmented angiogenesis and tumour growth." (PMID 39021279, 2024). "While the BOLD-MRI parameter, R2* value, shows the highest correlation with Hif-1α(r = 0.778, P < 0.001), indicating the capability of BOLD-MRI to evaluate tumor hypoxia." (PMID 38395884, 2024). "In a tumor xenograft model, it has been observed that since VEGF is transcriptionally activated by HIF-1α, the overexpression of filamin-A is able to increase HIF-1α recruitment to VEGF promoter, thus promoting tumor angiogenesis." (PMID 39156707, 2024). "The enrichment of OR family 7 in GBM is particularly noteworthy, as a member of this family, OR7E156P, was previously reported to promote tumor growth and invasion through the OR7E156P/miR-143/HIF1A axis." (PMID 39769144, 2024). "SMURF2: A Dual Role in Protein Degradation and Tumor Suppression: Under normoxic conditions, SMURF2 utilizes its E3 ubiquitin ligase activity to ubiquitinate and degrade HIF1α, maintaining low intracellular protein levels." (PMID 39697237, 2024). "In tumour vasculature, the PI3K/AKT/P70S6K pathway is responsible for HIF‐1α to induce VEGF for angiogenesis, suggesting that CCL5 regulates EPC angiogenesis via CCR5/AKT/P70S6K axis." (PMID 38899522, 2024). "Additionally, HIF-1α increases the expression of a protein called ADAM10 (a disintegrin and metalloproteinase domain-containing protein 10) in cancerous cells, causing major histocompatibility complex class I chain-related molecule (MICA) to be shed from a tumor cell's surface." (PMID 38165484, 2024). "When HIF-1α targets carbonic anhydrase IX (CAIX), the resulting complex catalyzes the conversion of CO2 to bicarbonate and protons, leading to tumor acidosis." (PMID 38879551, 2024). "HIF-1α and HIF-2α in tumors achieve hypoxic adaptation of tumor cells by inducing tumor angiogenesis and altering cellular energy metabolism." (PMID 39277981, 2024). "In solid tumors such as EC, hypoxic conditions stabilize hypoxia‐inducible factor‐1α (HIF‐1α), enhancing VEGF gene transcription and expression on tumor cells." (PMID 39415846, 2024). "HIF-1α-dependent COX2 activation is shown to promote proliferation, inflammation, and tumor metastasis." (PMID 38612478, 2024). "Taken together, our results indicate that the enforced expression of HIF1α and TGF-β2 can counterbalance the tumor-suppressive impact of TRIM55 in HCC." (PMID 39420007, 2024). "Dysfunction of complex I also leads to increased levels of α-ketoglutarate, alterations in Hypoxia-inducible factor-1α (HIF1α), generation of ROS, and activation of pyruvate dehydrogenase kinase 2 (PDK2), which accelerates tumor growth." (PMID 38737905, 2024). "Hypoxia/HIF1α regulated transcriptionally miR-5100 to promote the degradation of its target gene QKI, which acts as a tumor suppressor in HNSCC." (PMID 38485986, 2024). "In the clinical group Tumor status: Tumor free and with tumor, the genes TOP2A, BIRC5, VEGFA had highly statistical significance, while the genes HIF1A, ACSL3, FTH1 didn’t have statistical significance." (PMID 37248280, 2023). "HIF-1α is among the key factors responsible for CRC progression, anti-apoptosis, and tumor-supporting phenomena." (PMID 37749603, 2023). "HIF-1α and VEGFA are major regulators of tumor angiogenesis and of tumor progression in many types of cancer." (PMID 36678795, 2023).